CDC27 (cell division cycle 27)
Diseases named in the same sentence as CDC27 in open-access papers (continued):
Sharing a sentence is not in itself a finding about the gene and the disease.
tumor (continued). "Generally, CDC27 overexpression leads to proliferation, tumor formation, migration and invasion, and knock down of CDC27 gene inhibits these functions." (PMID 33750395, 2021). "The results showed that compared with the control group, knockdown of CDC27 in stable Jurkat cell contributed to a marked decrease in both tumor weight and volume (n = 5)." (PMID 32391258, 2020). "Only CDC27 protein expression levels was high in both the normal and tumor group in the HPA database." (PMID 33414811, 2020). "We also found that PD-L1 protein expression was increased in high-CDC27 expression areas of the tumor cells by an immunofluorescence assay." (PMID 32391258, 2020). "Firstly, we used immunohistochemistry to evaluate CDC27 expression in tumor tissues from 46 T-LBL patients and 30 cases of reactive hyperplasia of the lymph node tissues." (PMID 32391258, 2020). "The results demonstrated that CDC27 is not only related to tumor proliferation but also affects PD-L1 expression in T-LBL." (PMID 32391258, 2020). "In this study, we first found a prominent positive relationship between tumor CDC27 and PD-L1 expression by IHC staining of T-LBL tissues." (PMID 32391258, 2020). "CDC27 is a tumor suppressor and a core component of cell cycle progression and degradation of G1/mitotic checkpoint regulators." (PMID 30598078, 2018). "This analysis revealed that CDC27 was predominantly expressed in the nucleus, and tumor tissues showed a stronger staining intensity compared with paired adjacent non-tumor tissues." (PMID 26821069, 2016). "Results showed that CDC27 expression is significantly correlated with tumor progression and poor patient survival." (PMID 26821069, 2016). "Nevertheless, it suggests the possibility that curcumin targets Cdc27 in vivo to reduce tumor growth." (PMID 22280307, 2012). "Prior research has indicated that CDC27 may function as either a tumor suppressor or an oncogene in various neoplasms, and the activation of APC/C is thought to be linked to their pathogenesis." (PMID 38731925, 2024). "Furthermore, the discovery of tumor-specific CD4+ T cells, which recognize MHC II-restricted tumor antigens such as tyrosinase, CDC27, gp100, MAGE-3, Melan-A/MART-1, Eph receptor, and NY-ESO-1, underscores their importance in tumor immunity." (PMID 38887597, 2024). "Most of these functions, which are essential in tumor pathogenesis, may be regulated by CDC27 in APC/C." (PMID 38468345, 2024). "The changes in CDC27 level have been reported in differing neoplasms." (PMID 34126989, 2021). "Several patients had multiple CDC27 variants simultaneously, with one of the primary tumours of patients without relapse having 14 unique CDC27 mutations." (PMID 35008243, 2021). "It has been suggested that CDC27 may play either like a tumor suppressor gene or oncogene in different neoplasms." (PMID 33750395, 2021). "It has been suggested that CDC27 may play role either like a tumor suppressor gene or oncogene in different neoplasms." (PMID 33750395, 2021). "In particular, CDC27, a gene correlated with tumor progression and programmed death ligand-1 expression, was mutated in all responders and wild-type in all non-responders, which indicated great significance in predicting the treatment response of immunotherapy." (PMID 34025640, 2021). "Collectively, the detection of CDC27 expression could help to evaluate tumor staging and prognosis in T-LBL to a certain extent." (PMID 32391258, 2020). "It gave clues that CDC27 may influence PD-L1 expression via modulating certain potential CDKs and their cell cycle or apoptosis related downstream molecules in the tumor microenvironment." (PMID 32391258, 2020).
tumor (continued). "All of our functional studies in T-LBL cells demonstrated that CDC27 could promote tumor progression in various aspects." (PMID 32391258, 2020). "Our study revealed that CDC27 was overexpressed in T-LBL tumor tissues and correlated with OS." (PMID 32391258, 2020). "Furthermore, immunohistochemistry analysis of CDC27 and a proliferation marker, Ki67, was conducted and measured in tumor xenograft tissues, which revealed significantly higher levels of CDC27, but lower levels of Ki67, in the mir-218-2-inhibited group." (PMID 27974673, 2017). "High positive CDC27 expression was detected in 91 (54.8%) of the tumor tissue samples." (PMID 26821069, 2016). "The CDC27 is a gene possibly controlling the timing of mitosis and may have an important role in tumour cell division." (PMID 25496518, 2014). "Especially the abundant changes in CDC27 may be important in terms of regulating OS tumour cell division." (PMID 25496518, 2014). "However, there is also evidence indicating that CDC27 may act as a tumor suppressor in breast cancer." (PMID 35242701, 2022). "CDC27 dysregulation, either increased or decreased activity, may aggravate neoplasms." (PMID 33750395, 2021). "It has been proposed that CDC27 may also act as a tumor suppressor gene." (PMID 33750395, 2021). "However, we have not found the key mutations of CDC27 that can influence the tumor progression or tumorigenesis until now." (PMID 32391258, 2020). "A study showed that the pre-therapy tumor clone with mutations in CDC27 could not be detected after anti-PD-1 treatment in patients with hyperprogressive disease." (PMID 32391258, 2020). "Furthermore, unbiased genomic screens showed recently that dysfunction of CDC27, a member of the anaphase-promoting complex/cyclosome, limits excessive instability of cancer chromosomes, allowing tumor cells to dynamically improve their fitness during cancer evolution." (PMID 30591082, 2018). "In addition, CDC27 downregulation may stimulate efferocytosis and improve tumor microenvironment." (PMID 33750395, 2021). "Among the eight genes, five genes (BRCA1, TRIM37, RNF25, CDC27, and UBE2H) were significantly upregulated and three genes (RNF7, NPEPPS, and NCCRP1) were significantly down regulated in the tumor tissues." (PMID 33414811, 2020). "CDC27 is overexpressed in T-LBL tissues and influences the cell functions as well as PD-L1 expression, suggesting a novel insight into tumor progression and a new regulatory axis with potential therapeutic utility." (PMID 32391258, 2020). "Of the eight genes we identified, three genes (RNF7, NPEPPS, and NCCRP1) were down-regulated and the remaining five (BRCA1, TRIM37, RNF25, CDC27, and UBE2H) were up-regulated in tumor tissue compared to normal pancreatic tissue." (PMID 33414811, 2020). "Through immunohistochemistry staining, we identified that CDC27 was overexpressed in T-LBL tissues and related to tumor progression and poor survival." (PMID 32391258, 2020). "Taken together, our results indicate that CDC27 contributes to CRC cell proliferation via the modulation of ID1-mediated p21 regulation, which offers a novel approach to the inhibition of tumor growth." (PMID 26821069, 2016). "We also discovered that driver events in the private subclones of both samples, such as alterations in CDC27 and RUNX1, might have played a significant role in tumor progression or even neuroendocrine differentiation." (PMID 34646773, 2021).
tumor (continued). "A high-impact deletion in the CDC27 gene was detected only in tumours from patients with a relapse but in none of the tumours from patients without a relapse." (PMID 35008243, 2021). "Accordingly, we hypothesized that mir-218-2 may have a role in the regulation of CDC27 expression at the posttranscriptional level, leading to a dysfunction in APC/C and, ultimately, to abnormalities in tumor progression." (PMID 27974673, 2017). "On the other hand, CDC27 is an inducing factor for TGF-β, which modulates APC/C activity via phosphorylation, thereby resulting in the induction of genes responsive for growth inhibition and tumor suppression." (PMID 27974673, 2017). "In addition, 3 variants and 26 mutated genes, including CDC27, BCLAF1 and AQP7, were present in at least 30% of all primary tumours independent of prognosis." (PMID 35008243, 2021). "Results indicated that knockdown of CDC27 in HCT116 stable cell lines led to a significant decrease in tumor weight and volume compared with the control group (n=8), whereas mice injected with Dcdc27 cells exhibited greater tumor growth capacity compared with the control group (n=6)." (PMID 26821069, 2016). "In addition to KIT and KRAS, there was an over-representation of mutations in cell division cycle 27 (CDC27) (11.9%; 5 mutations, 5 tumours) and PRKRIR (4 mutations, 2 tumours), neither of which have been previously reported as TGCT drivers." (PMID 25609015, 2015). "Whatever the mechanism, curcumin's interaction with mitotic phosphorylated Cdc27 might provide a possible explanation why curcumin preferentially induces cell death in tumor cells that are usually highly proliferative and not in normal cells." (PMID 22280307, 2012). "Notably, CDC27 and FLG genes were mutated at the single-cell level but not detected in the corresponding tumor tissues, and they could promote cell growth by modulating the inflammatory response." (PMID 38870270, 2024).
cancer (32 papers, 2009 to 2026). A tumor composed of atypical neoplastic, often pleomorphic cells that invade other tissues. "In this malignancy, association between cancer signatures and germline polymorphisms of CDC27 was significant." (PMID 33750395, 2021). "In TNBC, it was reported that CDC27 downregulation is associated with modifying cell proliferation, migration and radio-sensitivity of the cancer cells." (PMID 34126989, 2021). "Interestingly, truncation mutations in the APC/C subunit CDC27 are frequently found in cancer, and cell lines engineered with these mutations display elongated mitotic timing and reduction of CIN." (PMID 36859339, 2023). "Cell division cycle 27 (CDC27) is an important core subunit of anaphase-promoting complex/cyclosome (APC/C), which has been found to be mutated in several malignant tumors, implying that CDC27 may be dysregulated in various types of tumors." (PMID 35242701, 2022). "It has been proposed that some germline variants in CDC27 may increase the susceptibility to cancers." (PMID 33750395, 2021). "Firstly, in recent years, CDC27 mutations have been found in some cancers." (PMID 32391258, 2020). "Curcumin binds the APC/C component CDC27 and cross-links its dimeric form thereby inducing programmed cell death, preferentially in cancer cells." (PMID 33937075, 2021). "Human studies about the role of CDC27 in cancer pathogenesis and its clinical importance are relatively few." (PMID 33750395, 2021). "In our analysis, 6 out of 18 genes (EIF4A3, RAN, PSMA3, CCNA2, POLR2D, CDC27) were scored as SL hits against RB1 in at least two human cancer cell lines screens." (PMID 33591981, 2021). "CDC27, especially in phosphorylated form, has been suggested as a biomarker for the evaluation of anti-cancer effects of curcumin." (PMID 33750395, 2021). "Based on current experimental basis, we hope that special inhibitors against CDC27 or its regulators can reactivate the anti-cancer effect of immune cells in T-LBL by reducing PD-L1 expression." (PMID 32391258, 2020). "In recent years, several studies have reported that CDC27 can facilitate cell proliferation, migration and invasion in some types of cancers." (PMID 32391258, 2020). "The third group contains four mitotic proteins (ANAPC5, CDC16, CDC20, CDC27) and shRNAs targeting these mitotic genes are predicted to sensitize cancer cells to GSK461364A." (PMID 22248814, 2011). "CDC27 functions as a vital part of the anaphase-promoting complex/cyclosome complex and its modified expression patterns can affect cell cycle progression and mitosis and cancer development and patient outcomes." (PMID 41487403, 2026). "Genes like SGK1, COP1, and CDC27 promote cell proliferation and regulate apoptosis in cancer cells." (PMID 37794118, 2023). "Most of these functions which are important in cancer pathogenesis may be regulated by CDC27 subunit in APC/C." (PMID 33750395, 2021). "On the other hand, downregulation of CDC27 may increase the cancer cell survival, decrease radiosensitivity and increase chemoresistancy." (PMID 33750395, 2021). "Also, in two distinct studies the interaction between Curcumin and CDC27 in various cancer cell types such as medulloblastoma and oral cancer cells has been investigated." (PMID 33750395, 2021). "More investigations are needed to discover the exact role of CDC27 in cancer." (PMID 33750395, 2021). "Here we review the molecular aspects that may affect CDC27 regulation from cell cycle and mitosis to cancer pathogenesis and prognosis." (PMID 33750395, 2021). "CDC27 is one of the main components of the anaphase-promoting complex/cyclosome and overexpression and variations in CDC27 expression may affect the cell cycle, mitosis, cancer pathogenesis and prognosis." (PMID 35008243, 2021). "CDC27 has been suggested as a prognostic biomarker in some cancers." (PMID 33750395, 2021).
cancer (continued). "EdU-647 labeling assays and cell cycle assays revealed that the cancer-promoting function of CDC27 may be primarily because of the promotion of the G1/S phase transition." (PMID 32391258, 2020). "Down or up-regulation of APC/C core subunits expression may have the same impact in cancer cells as it was reported that both CDC27 overexpression and CDC27 haploinsufficiency in CRC are correlated with poor patient survival." (PMID 29743633, 2018). "CDC27 haploinsufficiency is one of the 23 cancer driver genes identified in CRC30,43." (PMID 29743633, 2018). "Cell division cycle 27 (CDC27) is a core subunit of the anaphase-promoting complex/cyclosome, although the specific role of CDC27 in cancer remains unknown." (PMID 26821069, 2016). "Among the RNA targets that displayed a polysomal shift are mRNAs encoding proteins related to cancer, such as NRAS, the Ras-related protein R-Ras2, and those related to cell cycle, such as CDC27, the retinoblastoma binding protein RBBP8, and retinoblastoma-like 1 (RBL1)." (PMID 24842991, 2014). "Our studies provide a possible molecular mechanism why curcumin induces apoptosis preferentially in cancer cells and suggest that phosphorylation of Cdc27 could be used as a biomarker to predict the therapeutic response of cancer cells to curcumin." (PMID 22280307, 2012). "It has been proposed that CDC27 upregulation may increase stemness in cancer stem cells." (PMID 33750395, 2021). "Therefore, suppression of apoptosis by aberrant signaling pathways in most cancers may lead to increased CDC27 activity and cell cycle progression." (PMID 33750395, 2021). "The mutated CDC27, which has not been investigated thoroughly by a conventional approach, may play an important role in cancer development." (PMID 32391258, 2020). "CDC27 is a core subunit of APC/C, but the function of CDC27 in cancer remains unclear." (PMID 26821069, 2016). "MutSigCV analysis identified CDC27, PIK3CA, GATA3, CDH1, CTBP2, and CRIPAK as common cancer driver genes across both Ki67 expression groups (ZF13)." (PMID 37454130, 2023). "Therefore, the function of CDC27 may be cell- and tissue-specific in cancer." (PMID 35242701, 2022). "The findings above indicate there is a possibility that CDC27 is involved in CSC, and becomes a potential target of CSCs for monitoring the progress of cancer therapy and for evaluating new therapeutic approaches." (PMID 26821069, 2016). "Little is known about PPIC in cancer, however PPIA and another PPIase PIN1 have been shown to interact with key growth and signalling proteins including cyclin D1, CDK10, cdc27, and PLK1, with diverse downstream effects on MAPK signalling." (PMID 27852308, 2016). "PIK3CA, CBFB, CDC27, MAP3K1, and ESRRA were among the genes that were cancer drivers." (PMID 37454130, 2023). "In a number of cancer cell lines, miR-16 has been shown to be involved in the induction of apoptosis by targeting BCL-2 and in cell cycle regulation by targeting CDK6, CDC27, and CARD10." (PMID 21698265, 2011).
infection (8 papers, 2010 to 2021). The state of being infected such as from the introduction of a foreign agent such as serum, vaccine, antigenic substance or organism. "Infection of U2OS cells with pGLTR-X-PURO-CDC27 and induction with doxycycline resulted in mitotic arrest and CDC27 knockdown in a time and dose-dependent manner." (PMID 24841113, 2014). "CDC27 levels were significantly upregulated in RLE-6TN cells after infection with lenti-CDC27." (PMID 32710728, 2020). "We validated by qRT-PCR the downregulation of the cell division cycle pathway genes (CDC27 and CDC23) in HEK293T and human dermal fibroblasts upon infection with CHIKV." (PMID 24278205, 2013). "The data showed that at 8 and 24 h post-infection, specific silencing of USP22 and CDC27 inhibited bacterial replication throughout the intracellular infection period, compared to the negative control RNAi-treated or untreated cells." (PMID 20552012, 2010). "At 8 h post infection, only ∼20% of the USP22- and CDC27-silenced infected cells showed normal levels of replication." (PMID 20552012, 2010). "The results showed that at 12–24 h of infection the % of co-localization of the WT FCPs with both LAMP-2 and cathepsin-D positive compartments did not change from the 2 h time point in the CDC27, USP22, or PI4KCA RNAi-treated cells." (PMID 20552012, 2010).
hematologic malignancies (2 papers, 2021 to 2025). "Divergent variations in CDC27 DNA sequence and alterations in transcription of CDC27 have been detected in different solid tumors and hematological malignancies." (PMID 33750395, 2021). "Here, we reported that OSMI-1 could degrade the CDC27 protein through the ALP during the downregulation of the protein O-GlcNAcylation of CDC27 in hematologic malignancies." (PMID 39984622, 2025).
brain disorder (1 paper, 2024). A disease affecting the brain or part of the brain. "We found 7 variants that were associated with neurodevelopment and brain disorders, of which, 4 variants were found in both patients, namely in genes CTBP2, CDC27, UNC13D and IRF8, and 3 variants found in either of the patients, NDUFAF3, MRPS25, MORC3." (PMID 38638145, 2024).
kidney disease (1 paper, 2025). "To validate the potential genes is functionally in kidney disease, we choose whole genes (CDC16, CDC20, CDC27, MAD2L1, ANAPC1, ANAPC7, BUB1B) from first highest score subnetwork obtained from Cytoscape MCODE plugin from upregulated genes PPI as hub genes." (PMID 40034749, 2025).